IFNG (interferon gamma)
Diseases named in the same sentence as IFNG in open-access papers (continued):
Sharing a sentence is not in itself a finding about the gene and the disease.
infection (continued). "The thymus involution during infection is also attributed, at least partially, to the increased levels of TNFα and IFNγ." (PMID 38140683, 2023). "More specifically, the total number of IFNγ+ T cells increased progressively from Day 2 to Day 60 after infection in control mice that were only infected with MTB and in MTB-infected mice that received Tregs from air-exposed mice." (PMID 37965256, 2023). "Macrophages pre-primed with IFNγ showed slightly higher levels of Arg1 mRNA upon infection compared to unpolarised infected macrophages treated with IFNγ after onset of infection." (PMID 37190073, 2023). "Dose response studies showed strong IFNγ production at lower infection rates (0.25:1), although maximal responses were observed at an infection rate of 10:1." (PMID 38114497, 2023). "In the Med LN, at all time points following infection, the numbers of total cells, and numbers of Ifnγ+, CD4, and CD8 T cells were increased compared to naïve animals." (PMID 37842651, 2023). "Using IFNγ ELISpot and flow cytometry, we compared virus-specific CD4+ and CD8+ T-cell responses over 18 months post-infection with ancestral, alpha or delta SARS-CoV-2 variants and demonstrated that CD8+ TSCM is a relevant marker of long-term protection." (PMID 37046496, 2023). "Predisposition to high-intensity infection is also seen in applying TNF inhibitors and IFNγ-targeted biologic emapalumab." (PMID 38143753, 2023). "Initially, a Th1 response dominates, characterized by elevated levels of interleukin-2 (IL-2) and interferon-gamma (IFN-γ), persisting until the egg-laying phase (approximately 5 weeks after infection)." (PMID 38203591, 2023). "These experiments showed that the activity of GBP1 is restrained in uninfected cells but can be rapidly triggered upon infection by a pathogen that interferes with IFNγ-signaling." (PMID 37797010, 2023). "The particular role of Il12b in this process was revealed when both infection and IFNG activation are removed from the equation, i.e., the pre-stimulated, activated and infected macrophages are compared to activated and infected macrophages (M1-Ita vs. M1)." (PMID 37235312, 2023). "Th1‐like immune response with production of interferon gamma (IFN‐γ) is found in subclinical infection to moderate disease, while more severe disease is characterized by a Th2‐like immune profile." (PMID 38053473, 2023). "Influenza-specific IFNγ responses in lung MNCs were assessed in hamsters at days 4 and 14 post-infection." (PMID 37242338, 2023). "Tg infection drives the production of the inflammatory cytokine interferon gamma (IFNγ), which upregulates intracellular anti-pathogen defense pathways." (PMID 37975677, 2023). "Induced by IL-12 secreted by DCs, Th1 lymphocytes produce inflammatory cytokines, namely IL-2, IFNγ, and TNFα, while CTLs produce IFNγ, contributing to the clearance of the infection." (PMID 38076464, 2023). "The cumulative share of positive responses (to S1 and/or N) reached a maximum of 89% six months after the infection, followed by a gradual decrease so that at 18 months, only 22% of tested samples responded with a virus-specific expression of IFNγ." (PMID 37046496, 2023). "When tissue IFNγ levels have been measured after infection, they have ranged from 0.1 ng/ml to 10 ng/ml, showing that this is a physiologically relevant range." (PMID 37689116, 2023). "Upon infection of Paracoccidioides brasiliensis and H. capsulatum, IFNγ enhances the expression of MHCI, promoting antigen presentation, phagocytosis, and macrophage responses." (PMID 38143753, 2023). "Interferon gamma (IFNγ) is a potent antiviral cytokine that can be produced by many innate and adaptive immune cells during infection." (PMID 37842651, 2023). "Once activated, iNKT cells promptly produce various cytokines, including IFNγ, TNFα and IL-10 which actively recruit and activate neutrophils, macrophages, NK cells, and other immune cells to the site of infection." (PMID 37965344, 2023).
infection (continued). "Toxoplasma gondii induces a strong CD8 T cell response characterized by the secretion of IFNγ that promotes host survival during infection." (PMID 37287466, 2023). "Lung CD8+ T cells producing IFNγ following ex vivo antigen stimulation were also found in vaccinated mice 10d post infection, albeit in considerably lower numbers compared to what was observed with CD4+ T cells." (PMID 36732332, 2023). "While untreated wells demonstrated robust infection as indicated by >200 plaques per well, all doses of IFNγ significantly decreased plaque number." (PMID 37298195, 2023). "Type I interferons (IFNα/β) can be secreted by most cells upon infection, whereas type II IFNs (IFNγ) are secreted by specific cell types such as natural killer cells and T helper 1 cells." (PMID 37622993, 2023). "At day 5 post-infection, in parallel with the increase in the numbers of Ifnγ+ ILC1, NK, and NKT cells in the Med LN and lung, these cells increased the amount of Ifnγ they produced." (PMID 37842651, 2023). "For this purpose, murine bone marrow-derived macrophages (BMDMs) were differentiated ex vivo and subjected to IFNG stimulus and infection by L. infantum to obtain classically activated macrophages." (PMID 37235312, 2023). "By this time, high systemic IFNγ activates host cells to limit parasite replication and clear this lytic form of infection." (PMID 37675999, 2023). "The effector CD8+ T cells are one of the important sources of IFNγ, which is responsible for controlling both acute and chronic phases of infection." (PMID 37235437, 2023). "Infection promoted early expression of the Th1 cytokine IFNγ in the lungs at day 4 that dramatically rose by more than 10-fold at 7 dpi." (PMID 37795093, 2023). "Interferon gamma mRNA level peaked by day 4–6 post infection, implying that SARS-CoV-2 triggered the innate immune response." (PMID 36677472, 2023). "After transfer, these CTLs provided robust protection against infection with Listeria monocytogenes (LM) through a robust lytic response and IFNγ production." (PMID 37426662, 2023). "Antibacterial prophylaxis with trimethoprim-sulfamethoxazole, antifungal prophylaxis usually with itraconazole, and interferon gamma immunotherapy have been successfully used in reducing infection in CGD." (PMID 37764077, 2023). "For both IgG and IFNγ responses, when individuals were stratified according to previous infection status the difference between naïve cases and controls was no longer statistically significant." (PMID 37655880, 2023). "IFNγ responses to NP were found to be significantly (p = 0.0112) higher at day 14 post-infection compared to day 4 post-infection in older hamsters." (PMID 37242338, 2023). "Together, this suggests that IFNγ-induced early egress of Toxoplasma, and the enhanced clearance of ΔGRA57, ΔGRA70, and ΔGRA71 parasites, occurs later than 3 h post-infection of HFFs." (PMID 37459303, 2023). "Two recent studies found that ILC-derived IFNγ contributes to intestinal pathology during infection." (PMID 37483638, 2023). "We observed a 2.5-fold increase in the S-specific IFNγ-production at 20 months post-infection relative to 1 month post-infection, consistent with the increase of IFN producing CD8 + T cells measured by ICS." (PMID 37974069, 2023). "The infection caused a reduction of CRAMP production, activation in the interferon-gamma (IFN-γ)+ cells, and an increase in T1DM." (PMID 37374090, 2023). "The third patient also demonstrated anti-IFNγ auto-antibodies and suffered from recurrent infections with different species of NTM, Talaromyces, and Burkholderia pseudomallei." (PMID 38203686, 2023). "iNOS mRNA and protein expression increased after IFNγ pre- and post-stimulation conditions upon infection with S.tm as compared to the uninfected control, whereas IL-4 under pre- and post-stimulation conditions even reduced it below control conditions." (PMID 37190073, 2023).
infection (continued). "Serum cytokine responses are a helpful readout of systemic infection and are related to parasite burden; we, therefore, collected blood at various times post-infection and quantified IFNγ levels." (PMID 37675999, 2023). "In two systemic reviews of patients with anti-IFNγ auto-antibodies, 18.3%, respectively, 16.3% of these patients with anti-IFNγ auto-antibodies were diagnosed with talaromycosis, the second most common infection after NTM infections." (PMID 38203686, 2023). "In a murine model for African trypanosomiasis, it was shown that during the infection anti-IFNγ autoantibodies were induced." (PMID 38203686, 2023). "Sequestration seems to be particularly important during infection, with delayed virus clearance and prolonged IFNγ production." (PMID 36732425, 2023). "This cohort included four subgroups of individuals based on differing C. burnetii-specific IFNγ responses, serological status, and self-reported clinical symptoms during their initial infections." (PMID 37885896, 2023). "As the infection progresses, infiltrating CD4+ and CD8+ T cells are recruited to the site of infection producing type II IFN (IFNγ), as well as sentinel CD4+ and CD8+ resident memory T cells (TRMs) (12, –, 17)." (PMID 37655893, 2023). "As expected, in the spleen and lung, the numbers of Ifnγ+ cells returned to naïve levels of Ifnγ by day 40 post-infection." (PMID 37842651, 2023). "We further analyzed the active status of infiltrated immune cells during infection by measuring the levels of pro-inflammatory markers such as IFNγ, TNFα, and IL-6 in the lungs by Western blotting." (PMID 36676177, 2023). "Infections usually occur locally, and IFNγ is secreted locally by T cells after recognition of antigen-presenting target cells and can spread around 800 μm, the equivalent of 30–40 cell layers." (PMID 36732425, 2023). "In summary, our data demonstrate triphasic production of in vivo Ifnγ production, started by unconventional T cells and innate lymphoid cells early in infection, followed by effector T cells." (PMID 37842651, 2023). "BAL cytokines that were elevated peaked at mid-infection (42 days post inoculation) included, IL-6, IL-12, IFNγ, TNF, MIP-1β." (PMID 36893126, 2023). "A clear link in the cross-regulation of IFNα/β and IFNγ is also revealed by MHV-A59 infection in mice with conditional deletion of IFNAR in astrocytes (GFAPcre/IFNARfl/fl) or neurons (CaMKII cre/IFNARfl/fl)." (PMID 38140641, 2023). "This aligns with the high IFNγ levels observed in our severely infected patients and the higher IFNγIL-9 ratio in patients who later died of infection, making this IFNγ/IL-9 ratio a novel marker of disease severity." (PMID 37569646, 2023). "HFFs were pre-stimulated with 100 U/ml IFNγ for 24 h prior to infection with the mCherry expressing parasite lines or left untreated as a control." (PMID 37459303, 2023). "As determined by ELISPOT, by 4 dpi, the frequencies of IFNγ+ T splenocytes in the LV-DEN-immunized mice increased significantly compared to the pre-infection stage and were also higher than in the LV-GFP-injected mice." (PMID 37654495, 2023). "Immediate recruitment of neutrophils to the infection/inflammatory site is orchestrated by various chemokines such as interferon-gamma (IFN-γ), IL-8, leukotriene and C5a complement." (PMID 37212866, 2023). "In vivo data indicated that IFNγ and TNFα were involved in osteoclastogenesis and bone resorption during infection." (PMID 37153579, 2023). "The Molecule Activity Predictor tool was used to simulate the infection of SARS-CoV-2 by downregulating IFNG, which leads to the predicted activation of SNCA, and subsequently PD, through a dataset of intermediary molecules." (PMID 37686360, 2023). "In the current study, we found that IL-17+ and IFNγ+ T cells (mainly CD4+) are expanded in higher numbers following infection with Δhla, compared with WT." (PMID 36693884, 2023).
infection (continued). "Infection with the parasite Toxoplasma gondii leads to production of interferon gamma (IFNγ) that stimulates cells to upregulate defense proteins targeting the parasite for cell intrinsic elimination or growth restriction." (PMID 37975677, 2023). "The numbers of Ifnγ+ T cells peaked at day 10 post-infection with similar numbers of cytokine+ CD4 and CD8 T cells." (PMID 37842651, 2023). "IFNγ protein expression (directly ex vivo) was found only in YFP+ P14 CD8+ T cells in the skin during VacV-GP33 infection." (PMID 37402742, 2023). "•Plasmatic concentration of IgE, IL13 and IFNG was correlated with the infection intensities of S. mansoni." (PMID 36889485, 2023). "Anti-viral IFNλ2/3 (p = 0.002) and IFNγ (p = 0.0003) were also significantly decreased in severe infection." (PMID 37598150, 2023). "In the hDPP4 knockin mouse, where we observed the higher viral titer in the mouse lung from rGD01-nsp6-232F infection, we found higher production of inflammatory cytokines such as IFNγ, MCP-1, and IP-10." (PMID 38038429, 2023). "Throughout the infection and treatment period, we measured the levels of Interleukin-12 subunit alpha (IL-12), Interferon-gamma (IFN-γ), TNF, Tumor growth factor (TGF), and T lymphocytes using ELISA." (PMID 38036985, 2023). "Although NK cells are known to release interferon-gamma (IFN-γ) within hours after infection with T. gondii, these cells are very important in chronic inflammation." (PMID 37018796, 2023). "A Chinese study describes three patients with anti-IFNγ auto-antibodies with recurrent Salmonella bacteremia and two other patients with a single infection." (PMID 38203686, 2023). "To identify the impact of the associated molecules identified in both COVID-19 and SNCA, we placed these molecules into a pathway map, where IFNG was downregulated to simulate infection by SARS-CoV-2." (PMID 37686360, 2023). "GO analysis of the infection genes upregulated at one week indicated processes involved in immune responses and cytokine production, including responses to interferon-gamma and positive regulation of TNF, IL6, and IL1β production." (PMID 37200402, 2023). "Pro-inflammatory cytokines (IL-6, IFNγ, TNFα, and IL-12p40) as well as the anti-inflammatory cytokine IL-13 increased, whereas release of IL-1Ra (an IL-1β inhibitor) was reduced by infection with the mutant strain." (PMID 37669276, 2023). "Cases showed lower anti-S and -RBD IgG binding titer as well as lower S1- and S2-specific IFNγ T cell responses by ELISpot assay, compared with controls, with previous infection being an important driver of these responses." (PMID 37655880, 2023). "Vaccinated animals were found to have significantly higher levels of IFNγ responses prior to infection at 1 and 4 weeks after tonsil vaccination as compared to control animals." (PMID 36882405, 2023). "TRM upon encountering antigen stimulates IFNγ production and recruits memory T cell and other immune cell populations to the site of infection." (PMID 36881595, 2023). "Of note, the most marked change observed in IFNγ-/- mice upon infection was an increase in the GMP population." (PMID 37383236, 2023). "It was recently demonstrated that infection of specific macrophage subsets in the lamina propria is important for early production of IFNγ and promotes bacterial restriction in this compartment." (PMID 37216395, 2023). "IFNγ secretion in response to stimulation with C. burnetii antigen is known to be enhanced in those having experienced prior infection." (PMID 37885896, 2023). "Most of these studies examine peripheral blood mononuclear cells, although IFNγ+ CD8 T cells increase in the bronchoalveolar lavage fluid during challenge infections." (PMID 37842651, 2023). "Infection of IFNγ-stimulated HFFs with parasites containing a deletion in individual members of this putative complex led to enhanced host cell death, which was prevented when parasite egress was inhibited." (PMID 36916910, 2023).
infection (continued). "NK cells contribute to infection clearance by IFNγ production in the lungs however, NK cell production of IL-10 is detrimental to infected mice." (PMID 37486946, 2023). "To definitely exclude that T102 or T108 of Irga6 are targets of phosphorylation by ROP39, we enumerated p(T102)Irga6- and p(T108)Irga6-positive PVs using two phosphospecific antisera 2 h post infection of MEFs that had been stimulated for 24 h with IFNγ." (PMID 36603017, 2023). "At the same time, the relatively small share of E/TE CD4+ and CD8+ virus-specific T corroborated with the low share of positive results in IFNγ ELISpot assay beyond 9 months post-infection." (PMID 37046496, 2023). "nCD64 expression increases once these neutrophils are stimulated by the proinflammatory cytokines granulocyte colony-stimulating factor (G-CSF) and interferon gamma (IFN-γ), which are produced in response to infection or after exposure to endotoxin." (PMID 37746077, 2023). "IFNγ promotes innate and adaptive leukocyte recruitment to the site of infection through the induction of CCR2 and CXCR3 ligands." (PMID 37842651, 2023). "Lung CD4+ T cells displayed significantly increased Th1 (IFNγ) and Th2 (IL-4, IL-5, IL-13) cytokine production potential during pre-patent infection at the higher dose." (PMID 37012228, 2023). "Parasite infection leads to the production of the inflammatory cytokine interferon gamma (IFNγ) by natural killer and T cells." (PMID 37975677, 2023). "Infection with ply+lytA+ strain A66 induced detectable IFNγ, IL-6, TNFα, RANTES, IL-1α and IL-1β in the lungs of inoculated mice, and all but IL-1α in the bloodstream." (PMID 36897919, 2023). "Interleukin-1 (IL-1), Interleukin-6 (IL-6), Tumor Necrosis Factor-alpha (TNF-α), and Interferon-gamma (IFN-γ) are critical to cytokine storm/CRS resulting from infection/immunotherapy respectively." (PMID 37304291, 2023). "77% of participants free from serious infection with IFNγ-1b SC three times a week for one year compared to 30% of participants free from serious infection with placebo." (PMID 36911685, 2023). "In contrast to the sustained Ifnγ in the Med LN, the number of Ifnγ+ unconventional T cells and innate lymphoid cells returned to naïve levels by day 40 post-infection." (PMID 37842651, 2023). "T cells from infection-naïve patients usually secreted more IFNγ to vaccine-related peptides following the second vaccine (booster)." (PMID 36765532, 2023). "While the numbers of Ifnγ+ CD4 T cells remained stable, IAV infection did lead to a sustained increased in Ifnγ+ CD8 T cells up to 40 days post-infection." (PMID 37842651, 2023). "CD4+ T cells and interferon-gamma (INF-γ) were found to be the dominant immune agents against murine C. parvum infection as the IFN-γ produced by these cells is required for infection clearance." (PMID 37858196, 2023). "Conversely, IFNγ treatment alone significantly decreased the amount of infectious virus recovered from KC 24 h post infection." (PMID 37298195, 2023). "The RH and PRU mutant populations were both highly restricted in IFNγ-stimulated HFFs after 48 h of infection." (PMID 37459303, 2023). "In contrast to the effect of IFNγ, very few host genes were differentially expressed upon infection with RHΔGRA57 parasites compared to WT parasites." (PMID 37459303, 2023). "This again confirmed that previous infection was a strong determinant of both IgG and IFNγ responses to vaccination in this cohort." (PMID 37655880, 2023). "IL-10 is central in protecting host tissue during infection by inhibiting the synthesis of interferon-gamma (IFN-γ) synthesis by both T cells and NK cells." (PMID 36761779, 2023). "The classical activation of macrophages by IFNG before infection with L. infantum induced extensive changes in gene expression profiles compared to infected non-primed cells." (PMID 37235312, 2023).